ADAM3A (ADAM metallopeptidase domain 3A (pseudogene))
Synonyms: ADAM3AP; ADAM3; tMDCI; formerly CYRN1
Gene: Transcribed unitary pseudogene on chromosome 8 (39,455,339 to 39,522,810, reverse strand). Ensembl gene ENSG00000197475.
Diseases named in the same sentence as ADAM3A in open-access papers:
ADAM3A is named in the same sentence as 5 diseases in open-access papers, as found by Europe PMC text mining. Sharing a sentence is not in itself a finding about the gene and the disease. The quoted sentences say what the papers report.
non-small cell lung carcinoma (1 paper, 2022). A group of at least three distinct histological types of lung cancer, including non-small cell squamous cell carcinoma, adenocarcinoma, and large cell carcinoma. "In the literature, total deletion of ADAM3A was associated with poor prognosis in early-stage non-small cell lung cancer patients." (PMID 36553675, 2022).
tumor (7 papers, 2009 to 2022). "The specific gain of TLE4 and/or loss of ADAM3A loci and their association with tumor development, suggest important functions of these genes in the evolution of HEK293 cell lines, potentially through effects on proliferation and/or evasion of normal cell senescence of progeny cell lines." (PMID 33149219, 2020). "Mutation of the ADAM3A gene may decrease protein expression so as to change the intercellular adhesion, which may potentially affect the tumor microenvironment." (PMID 24952511, 2014). "After multivariate Cox analysis, advanced tumor stage (HR: 2.34, 95% CI: 1.37–4.00, p = 0.002) and total deletion or one copy of the ADAM3A and ADAM5 pseudogenes (HR: 1.68, 95% CI: 1.07–2.66, p = 0.02) were found to be predictors of poor EFS." (PMID 36553675, 2022). "We conducted an analysis of ADAM3A aberration in this tumor and paired normal sample by using GIANT." (PMID 24498045, 2014). "We also identified 44 lost segments, which harbored tumor suppressors including CDKN2A (9p21.3), ADAM3A (8p11.22), and CFHR1/CFHR4 (1q31.3)." (PMID 34070941, 2021). "In contrast, OncoSNP correctly identifies tumor ACN and cancer cell content, but fails to recognize the homozygous deletion of ADAM3A." (PMID 24498045, 2014).
ADAM3A also shares sentences with these, for which no sentence is quoted: cancer (1 paper); cleft lip (1); oropharynx cancer (1).